MIR6895 (microRNA 6895)
Synonyms: hsa-mir-6895
Gene: MicroRNA gene on chromosome X (53,195,411 to 53,195,488, reverse strand). Ensembl gene ENSG00000276575.
Homologues: Orthologues: chimpanzee MIR6895 (100% identical).